EFNB2 (ephrin B2)
Diseases named in the same sentence as EFNB2 in open-access papers (continued):
Sharing a sentence is not in itself a finding about the gene and the disease.
tumor (continued). "Ephrin-B2 is variably expressed in tumor cells and mediates tumor cell proliferation, invasion, and migration." (PMID 28489586, 2017). "All tumours presented cytoplasmic and membranous Ephrin-B2 expression in 25 to 90% of the tumour cells, as well as neurons, inflammatory cells and vascular endothelial cells, as reported." (PMID 27350048, 2016). "In patient samples stratified by GBM subtype, EFNB2 levels were highest in mesenchymal and classical tumours and correlated, inversely, with survival specifically in mesenchymal GBM." (PMID 27350048, 2016). "We have shown that ephrin-B2 drives two key aspects of tumour formation in our murine models: GSC perivascular invasion and proliferation." (PMID 27350048, 2016). "As our work is based on murine and human GSC models of GBM, and Ephrin-B2 levels are high in the GSC compartment in primary tumours, our findings indicate that anti-ephrin-B2-based therapies would target the most critical subset of cells within these lesions." (PMID 27350048, 2016). "In human GSC-derived orthotopic xenografts, EFNB2 knock-down blocked tumour initiation and treatment of established tumours with ephrin-B2-blocking antibodies suppressed progression." (PMID 27350048, 2016). "Ephrin-B2 was also found to drive the multiplication of the tumor cells independently of the protein’s interactions with the blood vessels." (PMID 27350048, 2016). "Second, it desensitizes the cells to extrinsic ephrin-B2 repulsion, thereby circumventing vascular confinement and permitting cells that have detached from the tumour mass to continue their migration along the vasculature." (PMID 27350048, 2016). "When tumours were divided into two groups on the basis of EFNB2 levels relative to median expression within subtypes, EFNB2 correlated with decreased survival in mesenchymal GBM." (PMID 27350048, 2016). "We conclude that GSC escape from endothelial compartmentalisation depends on continuous activation of Eph forward signalling elicited by elevated ephrin-B2 through homotypic cell-cell interactions within the tumour cell population." (PMID 27350048, 2016). "Inhibition of EphB4-Ephrin-B2 signaling blocks tumor angiogenesis, which in turn leads to hypoxia and induces VEGF expression." (PMID 23721559, 2013). "EphB4 activation leads to downstream activation of the phosphoinositide kinase-3 (PI3K) pathway in tumor cells, while Ephrin-B2 activation leads to activation of Src." (PMID 23721559, 2013). "We propose that high affinity and antagonist antibodies such as EC8 would provide a valuable tool for examining the role of ephrin-B2 expression on tumor angiogenesis and migration." (PMID 22292016, 2012). "Ephrin-B2 is preferentially expressed in arterial endothelium and smooth muscle cells, as well as neovasculature within the tumor." (PMID 22292016, 2012). "Ephrin-B2 also plays multiple roles in vessel maturation, and is expressed at substantial levels in KS, as well as in the KS tumor models we examined in this study." (PMID 23209418, 2012). "(iii) ephrin B2 expression was expressed at substantial levels in all KS cell lines and our immunohistochemical results detected ephrin B2, in vascular structures and tumor cells in KS xenograft tumors." (PMID 23209418, 2012). "Soluble extracellular domain of EphB4 targeting ephrin-B2 has been used in inhibiting angiogenesis and tumor growth in vivo." (PMID 22292016, 2012). "Ephrin-B2 is critical for the survival of KS tumor cells, while EphB4 is downregulated upon KSHV infection." (PMID 23209418, 2012). "Consistent with the previous observation of ephrin-B2 expression in tumor-associated vasculature, EC8 delineated ephrin-B2 expression in newly formed vessels within the tumor." (PMID 22292016, 2012). "EC8 staining of ephrin-B2 clearly differentiated tumor cells (marked with arrowhead) from the murine stroma (marked with arrow)." (PMID 22292016, 2012).
tumor (continued). "Targeting the ephrin-ephrin receptor interactions by antibodies, siRNA, or soluble ligands (e.g soluble EphB4, the receptor for ephrin-B2, fused to albumin) disrupts endothelial cell function and tumor vasculature." (PMID 23209418, 2012). "Ephrin-B2 is widely expressed in tumor blood vessels, where it is upregulated by hypoxia and vascular endothelial growth factor (VEGF)." (PMID 22194865, 2011). "EphB4-ephrin-B2 interaction is also known to play a critical role in angiogenesis, including blood vessel remodeling during embryonic development, tumor vascularization and other forms of pathological angiogenesis." (PMID 22194865, 2011). "The interaction between EphB4 expressed in circulating tumor cells and ephrin-B2 expressed in endothelial cells has also been reported to mediate site-specific metastatic dissemination." (PMID 22194865, 2011). "Dll4/Notch and Ephrin-B2/EphB4 pathways play critical roles in tumor vessel development and maturation." (PMID 21092311, 2010). "The monomeric form of the extracellular domain of EphB4 functions as an antagonist of EphB4-Ephrin-B2 signaling, thus blocking endothelial cell migration, tube formation and retards angiogenesis in tumor models." (PMID 21092311, 2010). "We sought to determine the effect of combined blockade of Dll4/Notch pathway (by sDll4) and Ephrin-B2/EphB4 pathway (by sEphB4-Alb) on tumor angiogenesis." (PMID 21092311, 2010). "sEphB4-Alb has been shown to be a potent inhibitor of tumor angiogenesis by blocking Ephrin-B2 and EphB4 signaling." (PMID 21092311, 2010). "In summary, targeting of Dll4/Notch and Ephrin-B2/EphB4 in combination showed marked improvement in tumor growth inhibition." (PMID 21092311, 2010). "Ephrin A3 (EFNA3) and Ephrin B2 (EFNB2) are ligands of the eph receptor family that plays a major role in tumor remodeling." (PMID 18549507, 2008). "Overexpression of ephrin-B2 led to an increase in tumour angiogenesis (vessel count by CD31 staining) but a decrease in tumour size and tumour cell proliferation (PCNA staining)." (PMID 15083195, 2004). "Tumours from ephrin-B2-sense-transfected cells had a significantly lower blood volume per gram of tissue than did tumours from pcDNA3-transfected cells (P=0.0288)." (PMID 15083195, 2004). "51Cr-labelled RBCs were injected intravenously via the tail vein into tumour-bearing mice (pcDNA3 and ephrin-B2 S2 transfectant, 10 mice/each group)." (PMID 15083195, 2004). "Immunohistochemical staining showed that the tumours overexpressing ephrin-B2 had increased vessel counts but decreased tumour cell proliferation." (PMID 15083195, 2004). "We found that overexpression of ephrin-B2 markedly decreased tumour growth in a mouse xenograft model." (PMID 15083195, 2004). "Immunohistochemical staining showed that ephrin-B2 transfectants produced higher tumour microvessel density and lower tumour cell proliferation than did parental or vector-transfected control cells." (PMID 15083195, 2004). "Tumours from ephrin-B2-transfected cells had a significantly smaller tumour blood volume despite having an increase in microvessel density." (PMID 15083195, 2004). "EFNB2, which is overexpressed in tumours, is a trans-membrane ligand specifically expressed in arterial endothelial cells." (PMID 14612907, 2003). "Finally, all transcriptomic investigations highlighted the constant involvement of epiregulin and ephrin B2, which are involved in cancer progression and tumour cell invasion, respectively." (PMID 39726234, 2025). "Additionally, endothelial expression of cellular communication network factor 1 (CCN1) promotes stable adhesion of tumor cells to blood vessels, while ephrin-B2 expression drives the perivascular invasion of tumor stem cells." (PMID 40995371, 2025). "EphB4 is thus required for initiation of the tumor in the context of PTEN deficiency, either through cell autonomous signaling or through simultaneous induction of its high affinity cell membrane bound ephrin-B2." (PMID 40044981, 2025).
tumor (continued). "Immunostaining studies show EphB4 expression is localized to the tumor core, while ephrin-B2 is more widely distributed, suggesting that EphB4-ephrin-B2 interactions may help retain tumor cells centrally and limit peripheral invasion." (PMID 41200151, 2025). "Alongside the various roles that endothelial cells play in supporting HGG growth, they have an intriguing role as tumor suppressors in the early stages of tumorigenesis via ephrin-B2 signaling, which compartmentalizes immortalized cells and inhibits invasion (Krusche and others 2016)." (PMID 39066464, 2025). "EFNB2 is a ligand for Eph receptors that is involved in angiogenesis and tumor metastasis." (PMID 38741195, 2024). "Interestingly, the overexpression of ephrin-B2 in CRC has been found to be associated with increased tumor angiogenesis, unexpectedly resulting in reduced tumor growth due to the structural abnormalities of the new vessels." (PMID 37610689, 2024). "In contrast, vascular EFNB2 acts as a promoter of local tumor growth and distant metastases." (PMID 39091728, 2024). "These vasculature genes included Efnb2, a member of the ephrin family and a pro-angiogenic factor whose overexpression predicts the poor prognosis of solid tumors, and Id1, a helix–loop–helix transcription factor that regulates tumor angiogenesis." (PMID 37047136, 2023). "EFNA5, EFNB1 and EFNB2 were found highly expressed in tumor tissues of ESCA." (PMID 37160815, 2023). "EFNB2 played a tumor-promoting role in CRC LM in vitro and in vivo." (PMID 36376513, 2023). "Elevated ITGA5 promotes LSCC tumor progression through upregulation of ephrin-B2 (EFNB2)." (PMID 36438491, 2022). "Finally, in line with ITGA5, EFNB2 was elevated in LSCC tumor tissues, predicted lymph node metastasis, and individuals with poor overall survival, and its expression levels were associated with mTORC1 activities and ITGA5 expression levels in primary tumors." (PMID 36438491, 2022). "EphB4/ephrin-B2 signaling may occur inefficiently in peripheral tumor sites of low cellularity, where cell–cell contact is rare." (PMID 35448036, 2022). "In the presence of its cognate ligand, EFNB2, it can act as a tumor suppressor." (PMID 35565468, 2022). "Based on this information, we hypothesised that the overexpression of sfTSLP promotes tumour growth through the downregulation of EFNB2." (PMID 33652749, 2021). "Furthermore, higher expression levels of ADAM9, EFNB2, MET, and TMOD3 were significantly associated with increased tumor infiltration of macrophages, DCs and/or B cells." (PMID 33648511, 2021). "Knocking down EFNB2 can block tumorigenesis and establish tumor therapy." (PMID 34167490, 2021). "In our future work, we are planning to overexpress EFNB2 in a transgenic mouse model to confirm whether the downregulation of EFNB2 is responsible for the tumour growth driven by sfTSLP overexpression." (PMID 33652749, 2021). "Trans-interaction between EphB4 and its membrane-bound ligand ephrin B2 (EFNB2) mediates bi-directional signaling: forward EFNB2-to-EphB4 signaling suppresses tumor cell proliferation, while reverse EphB4-to-EFNB2 signaling stimulates the invasive and angiogenic properties of endothelial cells." (PMID 31949258, 2020). "Similar to its role in the embryonic vasculature, Ephrin-B2 signaling may promote remodeling of immature tumor vascular networks, with the pruning of some vessels and enlargement of others." (PMID 32733636, 2020). "Functional studies showed that BIDEN-AP could simultaneously activate EphB4-initiated Abl/Crk1 tumor-suppressive signaling in tumor cells and inhibit EFNB2-regulated angiogenic signaling in endothelial cells." (PMID 31949258, 2020).
tumor (continued). "In this study, we addressed the question whether different regulators of the dermal compartment such as CRABP1, Nestin, and Ephrin B2 are markers preserved directly in the surrounding tumour stroma of skin appendages tumours." (PMID 31065284, 2019). "Ephrin B2 expression was detectable in the stroma of tumours but did also stain tumour cells." (PMID 31065284, 2019). "Considering the fact that the proteins encoded by the EFNB2 and FGF-1 genes act in multiple ways on stimulating tumor angiogenesis, β-escin may negatively influence angiogenesis by down-regulating these genes." (PMID 29342121, 2018). "Our data show that combining ephrin-B2-EphB4 inhibitor with RT significantly reduces regulatory T-cell and neutrophil infiltration, TGFβ1 secretion, and stromal fibrosis, enhancing effector T-cell activation and decreasing tumor growth." (PMID 30400822, 2018). "Moreover, the truncated and soluble EphB4 receptor prompts tumor angiogenesis upon stimulating ephrin-B2 signaling." (PMID 28194092, 2017). "Overall, these results suggest that the tumor suppressive effects of exogenous ephrin-B2-Fc might be due to Eph-B4 inhibition." (PMID 29190834, 2017). "In this study, we investigated whether ephrin-B2 expressed in OSCC contributed to tumor progression and lymph node metastasis." (PMID 29190834, 2017). "It is tempting to speculate that ephrin-B2-mediated vascular compartmentalisation might be a more general tumour-suppressive mechanism, limiting the spread of premalignant lesions across many cancer types." (PMID 27350048, 2016). "Thus, ephrin-B2 is expressed in stem-like cells invading along blood vessels in primary human tumours." (PMID 27350048, 2016). "Therefore, the dual function of EPHB4 as tumour promoter and suppressor is controlled by the absence and presence of EFNB2 in cancer cells." (PMID 28035996, 2016). "Importantly, many perivascular ALDH1+ neoplastic cells at the infiltrative tumour margin co-expressed ephrin-B2." (PMID 27350048, 2016). "Remarkably, EFNB2 knock-down in primary human GSC isolated from patient material or treatment of established tumours derived from these GSC with anti-ephrin-B2 single chain blocking antibodies strongly suppressed tumourigenesis, by concomitantly inhibiting vascular association and proliferation." (PMID 27350048, 2016). "Second, we asked whether Ephrin-B2 inhibition could suppress tumourigenesis of pre-established tumours." (PMID 27350048, 2016). "Indeed, lgT-immortalised stem cells overexpressing Efnb2 formed aggressive tumours with nearly identical kinetics to Ras-transformed cells and genetic deletion of Efnb2 in GSCs significantly delayed tumourigenesis." (PMID 27350048, 2016). "Importantly, both phenotypes can be restrained by stimulation with ephrin-B2 proving that over-production of EphB4 contributes in a ligand-independent mechanism and that ligand-dependent stimulation is tumour suppressive." (PMID 25831049, 2015). "VEGF and EFNB2 showed a contrary gene expression in small and larger tumours with lymphatic spread." (PMID 26044849, 2015). "Tumour cells expressing dominant negative EphB4 incapable of forward signaling but able to stimulate ephrin-B2 reverse signaling, attracted endothelial cells, stimulating cell invasion, survival and proliferation and this correlated with tumours with larger blood vessels and a higher blood content." (PMID 25831049, 2015). "Gene expression of EFNB2 correlated with tumour size and tumour differentiation." (PMID 26044849, 2015). "We further examined if EC8 could be applied to detect ephrin-B2 expression in other types of tumor directly collected from human patients." (PMID 22292016, 2012). "It is unknown how ephrin-B2 upregulation in some of the tumors of epithelium origin would perturb the balance between ephrin-B2 and Eph4 expressed in arterial and venous vessels, respectively, and contribute to the tumor growth and metastasis." (PMID 22292016, 2012).
tumor (continued). "The role of EphB4 and ephrin-B2 also extends to tumor growth and angiogenesis." (PMID 22292016, 2012). "Additionally, ephrin-B2-induced EphB4 forward signaling in endothelial cells likely contributes to tumor angiogenesis." (PMID 22194865, 2011). "The EphB4 receptor tyrosine kinase together with its preferred ligand, ephrin-B2, regulates a variety of physiological and pathological processes, including tumor progression, pathological forms of angiogenesis, cardiomyocyte differentiation and bone remodeling." (PMID 22194865, 2011). "Thus, an important role of EphB4 during tumor progression is to promote ephrin-B2 reverse signaling in the vasculature." (PMID 22194865, 2011). "Finally, in addition to improved anti-tumor efficacy, simultaneous blockade of Dll4/Notch and Ephrin-B2/EphB4 abolished the liver vascular lesions seen when only Dll4/Notch is inhibited." (PMID 21092311, 2010). "Interestingly, it has recently been reported that tumor cells expressing EphB receptors were restricted to large homogeneous clusters by the ligands ephrin-B1 and ephrin-B2." (PMID 20624275, 2010). "To examine whether synchronous suppression of Dll4/Notch and EphB4/Ephrin-B2 signaling pathways might result in greater inhibition of RT2 tumor development, we treated RT2 Dll4+/- mice with sEphB4-Alb." (PMID 21092311, 2010). "Interestingly, over-expression of ephrin B2 in colorectal cancers (CRCs) appears to correlate with increased tumour angiogenesis, unexpectedly resulting in reduced tumour growth as new vessels were malformed." (PMID 19277044, 2009). "This may be because the EphB4 ectodomain exerted a chemoattractive effect on endothelial cells through ephrin-B2 expressed on these cells and promoted endothelial cell proliferation and survival resulting in more tumour vasculature." (PMID 16171530, 2005). "Although ephrin-B2 transfection increased tumour vessel density, the decrease in blood perfusion suggests that these vessels may be ‘dysfunctional’." (PMID 15083195, 2004). "Using 51Cr-labelled red blood cells (RBCs) to determine the functional blood volume in tumours, we demonstrated that tumours from ephrin-B2-transfected cells had significantly decreased blood volume compared with tumours from parental or vector-transfected control cells." (PMID 15083195, 2004). "This apparent paradox could be explained by the development of an inefficient blood supply in the ephrin-B2-overexpressing tumours." (PMID 15083195, 2004). "Further studies suggest that ephrin-B2 is involved in tumour angiogenesis." (PMID 15083195, 2004). "To determine whether overexpression of ephrin-B2 affects the growth of KM12L4 tumours, we injected KM12L4 tumour cells transfected with a sense construct for ephrin-B2 subcutaneously in nude mice." (PMID 15083195, 2004). "Interestingly, ephrin-B2 knockdown in GBM xenografts paradoxically increases tumor growth." (PMID 41200151, 2025). "However, EFNB2 displayed tumor-suppressive effects, which were more pronounced in BPH1 cells." (PMID 35565468, 2022). "Furthermore, EPHRIN B2 could be applied to the antigen-recognition domain of the CAR construct to harness EPHB4-expressing tumor cells to genetically modify CAR-T cells that lack the proliferative tendency of tumor cells via ligand-antigen interaction." (PMID 33816783, 2021). "Thus, we propose a role for Ephrin-B2 in promoting efficient tumor vascularization." (PMID 32733636, 2020). "Independent of interaction with EFNB2, EphB4 can be activated by ligand-independent pathways to promote proliferation and metastasis, as EphB4 mutants with mutated phosphorylation sites can still promote tumor cell growth and migration." (PMID 31949258, 2020). "Furthermore, we found that ephrin-B2 expression was correlated with the malignant potential of OSCC cells, suggesting that ephrin-B2 might regulate tumor progression in OSCC." (PMID 29190834, 2017).